SMAD3 (SMAD family member 3)
Diseases named in the same sentence as SMAD3 in open-access papers (continued):
Sharing a sentence is not in itself a finding about the gene and the disease.
glioblastoma (28 papers, 2014 to 2026). The most malignant astrocytic tumor (WHO grade IV). "Lower levels of Smad3 may lead to the loss of apoptosis sensitivity in response to NAG-1 in some glioblastoma cell lines." (PMID 24759784, 2014). "Further, we discovered that APOC1 inhibition downregulates TGFβ2 and disrupts its associated downstream SMAD3 and pSMAD3, revealing a new signaling pathway involving the miR-660-3p/APOC1/TGFβ2 axis in the development of glioblastoma." (PMID 37981873, 2023). "Inhibition of SMAD3 and neuronal activity stimulation cooperate to promote proliferation of glioblastoma cells in co-culture with glutamatergic neurons, and in mice bearing patient-derived xenografts." (PMID 37833281, 2023). "TGFβ1 induces THBS1 (thrombospondin-1) expression via Smad3, which contributes to invasive behavior during glioblastoma expansion; TGF-β also stimulates both THBS1 and CISP/THBS2 synthesis by bovine adrenocortical cells." (PMID 36535930, 2022). "In the present study, we also found the direct interaction between Akt and Smad3 and elevated levels of NAG-1-induced Smad3 phosphorylation by PI3K inhibitors in glioblastoma cells." (PMID 24759784, 2014). "The PI3K inhibitors promoted NAG-1-induced glioblastoma cell apoptosis, while siRNAs to Smad2 and Smad3 decreased the apoptosis rate." (PMID 24759784, 2014). "In glioblastomas, miR-18a has been reported to repress tumor progression through targeting SMAD3 and CTGF." (PMID 25069832, 2014). "In addition, it has been reported that upregulated LAMP2A-mediated hyperactivation of CMA in human grade IV glioblastoma regulates malignant progression of tumor cells by targeting SMAD3 degradation." (PMID 38717639, 2024). "Our data found that TGF-β1 could increase ROS levels in the human glioblastoma cells and was inhibited by the Smad3 inhibitor SIS3 and the NOX4 selective inhibitor GKT137831 (10 μM)." (PMID 34257808, 2021). "For example, some studies proposed that miR-92b-3p could promote the proliferation of glioblastoma cells by inhibiting the TGF-β/Smad3/p21 signaling pathway and inhibited cell apoptosis by targeting the PTEN/Akt signaling pathway." (PMID 34283053, 2021). "NAG-1 could induce the phosphorylation of PI3K/Akt and Smad2/3 in all six tested glioblastoma cell lines, except Smad3 phosphorylation in A172 and LN-229 cell lines." (PMID 24759784, 2014). "NAG-1 also stimulated the direct interaction between Akt and Smad3 in glioblastoma cells." (PMID 24759784, 2014). "The interaction between SMAD3 and EP300 enhances the expression of mesenchymal markers associated with the mesenchymal subtype of glioblastoma multiforme (GBM)." (PMID 40066091, 2025). "Furthermore, to determine whether NOX4 was regulated by TGF-β1 through the Smad pathway, the glioblastoma cells were transfected with si-NC or si-Smad3." (PMID 34257808, 2021). "The selected GSC superenhancers were enriched for transcriptional motifs, including NR4A2, SMAD3, and ETV4, which have been previously reported to promote glioblastoma malignancy." (PMID 36394953, 2023). "For example, miR-92b-3p expression is up-regulated in glioblastoma and promotes cell proliferation by inhibiting the TGF-β/Smad3/p21 signaling pathway." (PMID 34283053, 2021). "VEGF was released in glioblastoma by TGFβ regulation, leading to the phosphorylation of SMAD2, SMAD3, and SMAD1/5/8 and increased VEGF release." (PMID 34067437, 2021). "QKI suppresses TGF-β signaling in glioblastoma, and SKP1 is an essential component of the E3 ubiquitin ligase complex ROC1-SCFFbw1a, which induces Smad3 ubiquitination." (PMID 25971746, 2015). "Here we reported that NAG-1 overexpression could activate PI3K/Akt and Smad2/3 signaling cascades in glioblastoma cells, and that NAG-1-induced apoptosis was enhanced by PI3K inhibitors and decreased by siRNAs to Smad2 and Smad3." (PMID 24759784, 2014).
glioblastoma (continued). "ZDHHC19‐mediated SMAD family member 3 (Smad3) palmitoylation at Cys421 enhances activation of the transforming growth factor (TGF) signaling pathway, and Smad3 interaction with E1A binding protein P300 (EP300) promotes mesenchymal‐like transition in the mesenchymal subtype of glioblastoma (GBM)." (PMID 36018061, 2023). "There was positive correlation between the miR-148a levels in 10 freshly collected glioblastoma samples with MMP9 (r = 0.674, P < 0.001) and VEGF mRNA levels (r = 0.748, P < 0.001), the DNA-binding activity of NF-κB (r = 0.895, P < 0.001), and p-Smad3 expression (r = 0.754, P = 0.001)." (PMID 25971746, 2015). "Furthermore, the interaction between SMAD3 and EP300 promotes the expression of mesenchymal markers in the mesenchymal subtype of glioblastoma multiforme (GBM)." (PMID 38415253, 2024).
atherosclerosis (27 papers, 2008 to 2025). A disease characterized by the build-up of fatty material and calcium deposition in the arterial wall resulting in partial or complete occlusion of the arterial lumen. "SMAD3 regulates macrophage activation in renal inflammation and also regulates the expression of miR-21, which is involved in inflammation associated with atherosclerosis." (PMID 38791063, 2024). "We found no other published articles investigating the influence of the rs17228212 polymorphism on the expression of SMAD3 in atherosclerosis." (PMID 38791063, 2024). "One TGFβ family member, SMAD3, has been experimentally linked to atherosclerosis, recently associated with CAD, and implicated with genomic and functional studies as the causal gene at 15q22.33 by this and another laboratory." (PMID 30307970, 2018). "A recent study showed that TEAD3 is required for TGFβ signaling through association with Smad3 in human aortic SMCs in a risk locus for atherosclerosis." (PMID 29342503, 2018). "Similarities between atherosclerosis and RA, as both are chronic inflammatory diseases that exhibit similar pathophysiological mechanisms, made conceivable the search for a potential association of SMAD3 rs17228212 gene variant with CV disease in RA." (PMID 24204921, 2013). "circSMAD3, derived from the SMAD3 gene, was identified to be significantly downregulated in vascular injury and atherosclerosis." (PMID 39219022, 2025). "In regard to atherosclerosis, TCF21 is induced early during atherosclerosis development to suppress SMAD3-mediated gene expression and allow SMCs to switch to a fibromyocyte phenotype." (PMID 37325472, 2023). "A recent study in the context of atherosclerosis using SMC-specific Smad3 deleted mice further highlight Smad3 as a key protective transcription factor again the formation of atherosclerotic plaques and vascular calcification." (PMID 36685215, 2022). "CircRNA-0003204 inhibits the proliferation, migration and tube formation of ECs in atherosclerosis through the miR-370-3p/TGFβR2/p-SMAD3 axis." (PMID 35366240, 2022). "In summary, our study provided new evidence that Rb2 inhibited M1 polarization, lipid accumulation, and atherosclerosis plaque progression by counteracting miR-216a through the Smad3/IκBα pathway." (PMID 35046806, 2021). "The circular RNA circ_0003204 inhibits the proliferation, migration and tube formation of endothelial cells in atherosclerosis via the miR-370-3p/TGFβR2/phosph-SMAD3 axis." (PMID 34872444, 2021). "This animal study focused on the gene therapy manipulation of the very powerful TGFβ1 signal transduction pathway for inhibiting atherosclerosis, by the delivery of the human SMAD3 gene." (PMID 25236373, 2014). "In the ApoE knockout mice model of atherosclerosis we have recently found that atorvastatin increased Smad3 phosphorylation and ECM-related proteins, including CTGF, PAI-1 and type I collagen in the fibrous cap." (PMID 21152444, 2010). "Although the mechanism of action of SMAD3 is quite well understood, there are not many genetic association studies in the field of atherosclerosis." (PMID 38791063, 2024). "Therefore, research on larger and more ethnically diverse subjects is needed to improve our understanding of the role of SMAD3 in the development of atherosclerosis." (PMID 38791063, 2024). "SMAD3, TNF, MMP2, MMP9, CTGF, CD44 and AKT1 are associated with atherosclerosis." (PMID 37328880, 2023). "On the one hand, HIF-1α activation was shown to promote atherosclerosis initiation and progression as well as hypoxia-induced renal fibrogenesis by stimulating epithelial-to-mesenchymal transition and a2(I) collagen expression through interactions with Smad3." (PMID 34572324, 2021). "NaHS injection could suppress the formation of atherosclerosis and degradation of both TGF-β and Smad3 phosphorylation, but PPG administration resulted in more decrease of TGF-β protein level and Smad3 phosphorylation and promote atherosclerosis formation." (PMID 33276745, 2020).
atherosclerosis (continued). "In the correlation of TGF-β1 and SMAD3 levels with the risk factors of CAD, TGF-β1 is closely related to Lp(a) and uric acid, which both are considered to be markers of atherosclerosis, indicating that this cytokine may contribute to the establishment of CAD by regulating atherogenesis." (PMID 24533640, 2014). "One interaction between SMAD3 and NEDD9 on HDL-C was further replicated in an independent sample from the Multi-Ethnic Study of Atherosclerosis." (PMID 23468652, 2013). "One of these suggestive gene-level interactions, between SMAD3 and NEDD9 on the levels of HDL-C, is significantly replicated in an independent cohort from the Multi-Ethnic Study of Atherosclerosis (MESA)." (PMID 23468652, 2013). "We identified five novel interactions that are not evident from marker-based interaction testing and successfully replicated one of these interactions, between SMAD3 and NEDD9, in an independent sample from the Multi-Ethnic Study of Atherosclerosis." (PMID 23468652, 2013). "Downregulated genes (SYK, SMAD3, S100A4, and FERM3) were expected to be involved in inhibiting cellular recruitment by IPA, and were previously documented to enhance the beginning and progression of atherosclerosis." (PMID 35806463, 2022). "The results were compared to biopsies from patients with atherosclerosis in which no staining for total SMAD3 was observed." (PMID 31475485, 2019). "Relevant to atherosclerosis and CAD, SMAD3 has been shown to directly bind the SMC lineage determining transcription factor myocardin (MYOCD) to regulate transcription of differentiation factors and linked to differentiative and anti-proliferative effects in a number of smooth muscle cell models." (PMID 30307970, 2018). "SMAD3 and MIA3 are important for vascular stability and angiogenesis, fundamental processes for plaque development and atherosclerosis, although the mechanisms are not fully known." (PMID 28737528, 2017). "Our results revealed that SMAD3 rs17228212 gene variant is associated with lower risk of CVA and less severe subclinical atherosclerosis in RA patients negative for anti-CCP antibodies." (PMID 24204921, 2013). "In summary, our results revealed that SMAD3 rs17228212 gene variant is associated with lower risk of CVA and less severe subclinical atherosclerosis in RA patients negative for anti-CCP antibodies." (PMID 24204921, 2013). "Our results indicate a potential association of the SMAD3 rs17228212 gene variant with CVA and subclinical atherosclerosis in RA patients who are negative for anti-CCP antibodies." (PMID 24204921, 2013).
chronic kidney disease (27 papers, 2013 to 2025). Impairment of the renal function secondary to chronic kidney damage persisting for three or more months. "The aim of this study was to investigate the consequence of Smad3 deficiency in TGF‐β1‐induced chronic kidney disease with special emphasis on ECM turnover and MMP regulation." (PMID 24744860, 2013). "Activation of TGF-β pathway (largely driven by TGF-β1 isoform) in fibrosis and potent upregulation of Smad2 and Smad3 proteins have been demonstrated both in human and in animal models of chronic kidney disease." (PMID 27610006, 2016). "Given the findings from the recent years that emphasize its significance in chronic kidney diseases as well as in inflammatory reaction, this review will focus on miR-21 and its therapeutic potential, as well as on its key upstream regulator—Smad3." (PMID 27610006, 2016). "Consistent with the consensus that Smad3 stimulates tissue fibrosis in a number of chronic kidney diseases, inhibition of Smad3 transcription and phosphorylation was a mechanism through which NG inhibits fibrosis in vitro and in vivo." (PMID 26474462, 2015). "Transforming growth factor-β/Smad3 signaling plays a critical role in the process of chronic kidney disease (CKD), but targeting Smad3 systematically may cause autoimmune disease by impairing immunity." (PMID 26648110, 2015). "This may be a shortcoming of the postulated beneficial therapy targeting Smad3 in patients with chronic kidney diseases, and call for cell‐targeted intervention strategies." (PMID 24744860, 2013). "In patients with chronic kidney disease (CKD) and the fibrotic kidneys of animal models, Smad2 and Smad3 are highly active." (PMID 36835428, 2023). "The study aims to reveal new insights into the impact of Tempol on specific, both known and unknown, signaling pathways in chronic kidney disease (CKD), with a focus on the regulation of NF-κB and TGF-β1/Smad3 pathways." (PMID 38395806, 2024). "Nrp1 interacts with both TGF-β and TNF-α receptors in distal TECs while activating the Nfkb1 and Smad3 pathway, regulating the secretion of collagen, suppressing OXPHOS, activating myofibroblasts, thereby accelerating the progression of acute and chronic kidney diseases." (PMID 38977708, 2024). "Thus, the role of Smad3 on MMP regulation, GBM, and tubular basement membrane (TBM) remodeling in chronic kidney disease in vivo needs to be clarified." (PMID 24744860, 2013). "This was examined in vivo in a transgenic model of TGF‐β1‐induced chronic kidney disease with Smad3 or without Smad3 expression and in vitro in mesangial cells and glomerular endothelial cells with Smad2/3 inhibitors or Smad3‐knockdown." (PMID 24744860, 2013). "The incidence of acute kidney injury (AKI) and chronic kidney disease (CKD) is reduced in mice lacking Smad3, suggesting that genetic deletion or pharmacological inhibition of Smad3 may help reduce kidney damage in mouse models of ischemia-induced kidney disease." (PMID 40243751, 2025).
glioma (26 papers, 2012 to 2025). A benign or malignant brain and spinal cord tumor that arises from glial cells (astrocytes, oligodendrocytes, ependymal cells). "Based on these studies and the results of the present study, we hypothesized that the differences in the molecular structures of Smad2 and Smad3 may be the reason underlying why Smad3 has a significant effect on the regulation of TGFβ2-induced cell proliferation in glioma cells." (PMID 25891822, 2015). "These and other SMAD3/PITX1 downstream targets also present different expression levels in high-grade glioma (HGG) and low-grade glioma (LGG) tissue samples from the human protein atlas." (PMID 37833281, 2023). "GO terms related to TGF-β receptor activity are significantly enriched among the SIX1 downstream targets, which links TGF-β signalling via SMAD3 to the synaptic communication between neurons and glioma cells." (PMID 37833281, 2023). "Overexpression of let-7a has an antimetastatic effect on glioma cells by negatively regulating the TGF-β1/Smad3 signaling pathway." (PMID 32714407, 2020). "Analyses of The Cancer Genome Atlas (TCGA) and Chinese Glioma Genome Atlas (CGGA) verified the expression levels and prognoses associated with RUNX1/p-SMAD3/SUV39H1 target genes." (PMID 31754093, 2019). "Our integrated genomic analyses of LGG and GBM indicate a potential new role for PJA1 in gliomas, potentially through its preciously demonstrated ubiquitination of the Smad3-likely reflecting the TGF-β tumor suppressor role in this cancer." (PMID 28966725, 2017). "Above findings provided evidence for the essential roles of TGF-β/Smad3 signaling pathway in mediating miR-21 secretion in glioma." (PMID 27166186, 2016). "TGF-β/Smad3 signaling was identified to participate in mediating the release of miR-21 from glioma cells." (PMID 27166186, 2016). "In the second phase, we demonstrated that cultured glioma cells secreted miR-21 into extracellular medium, and TGF-β/Smad3 signaling pathway was involved in the secretory regulation of miR-21 in glioma cells." (PMID 27166186, 2016). "Previous studies have investigated the expression levels of Smad2 and Smad3 in gliomas in tumor specimens and cell lines, however, the results have been inconsistent." (PMID 25891822, 2015). "The results revealed that the protein expression levels of Smad2 and Smad3 were lower in the glioma cell lines compared with normal astrocytes." (PMID 25891822, 2015). "The present study investigated how downregulation of the expression levels of Smad2 and Smad3 affected glioma cell proliferation." (PMID 25891822, 2015). "The results revealed that the knock down of Smad2 and Smad3 enhanced cellular proliferation, demonstrating that Smad2 and Smad3 had an inhibitory effect on cell proliferation in this glioma cell line." (PMID 25891822, 2015). "GB cells exhibit extensive chromatin rewiring, reshaping the enhancer landscape and regulatory chromatin loops to sustain transcriptional programs that promote neuron–glioma interactions, with key transcription factors (TFs) like SMAD3 and PITX1 orchestrating these adaptations." (PMID 40685688, 2025). "Smad3 and hypoxia-inducible factor 1-alpha may be important molecular targets for treatment of glioma because they appear to coordinate the basic aspects of cancer stem cell biology." (PMID 34707087, 2021). "In this investigation, we performed bioinformatic analyses to examine Praja1 and Praja2 expression across 29 cancer types, and observed raised levels of Praja1 and Praja2 in gliomas with an inverse relationship between Praja1 and apoptotic genes and Praja substrates such as Smad3." (PMID 28966725, 2017). "Consistently, the expression of phosphorylated Smad3 was higher in the SMC4-overexpressing glioma tissues and lower in the SMC4-silenced tissues compared with control tumor tissues, respectively, which further support the notion that SMC4 contributes to activation of TGFβ/Smad signaling." (PMID 28287612, 2017).